Y_RNA (Y RNA )
Gene: Miscellaneous RNA gene on chromosome 1 (39,944,890 to 39,944,998, reverse strand). Ensembl gene ENSG00000207356.
Homologues: Orthologues: chimpanzee Y_RNA (100% identical), macaque Y_RNA (97% identical), dog Y_RNA (91% identical), guinea pig Y_RNA (90% identical). Paralogues in human: RNY1 (91% identical), Y_RNA (89% identical), Y_RNA (88% identical), Y_RNA (87% identical), Y_RNA (86% identical), RNY1P11 (85% identical), Y_RNA (85% identical), RNY1P8 (84% identical), Y_RNA (84% identical), Y_RNA (83% identical), RNY1P10 (83% identical), RNY1P7 (83% identical), and 100 more.